CASR (calcium sensing receptor)
Diseases named in the same sentence as CASR in open-access papers (continued):
Sharing a sentence is not in itself a finding about the gene and the disease.
breast carcinoma (continued). "The activation of an expressed CaSR on two human breast cancer lines, MDA-MB-231 and MCF-7, led to increased production of parathyroid hormone-related protein (PTHrP)." (PMID 37511437, 2023). "Elevated levels of calcium ions in breast cancer cells then promote the production of PTHrP, likely through a mechanism mediated by the CaSR." (PMID 37511437, 2023). "The CaSR has been found in breast cancer cell cultures, and it has been shown that the expression of this receptor is directly associated with the occurrence of bone metastases." (PMID 37511437, 2023). "Mice with inhibited CaSR in breast cancer cells exhibited slower tumor growth and longer survival compared to the control group." (PMID 37511437, 2023). "Studies on mice and breast cancer cell cultures have shown that inhibition of the CaSR reduced the proliferation of breast cancer cells, and in mice with CaSR inhibition, there was slower tumor growth and longer survival compared to the control group." (PMID 37511437, 2023). "The role of the CaSR in the development of bone metastases has already been described in breast cancer cells." (PMID 37511437, 2023). "Even though little is known about the calcium-sensing receptor, its activation increases the influx of calcium across the membrane in breast cancer cells." (PMID 37345127, 2023). "In the case of breast cancer, when the presence of the CaSR through positive feedback mechanisms leads to increased bone resorption, it has been shown that there is downregulation and decreased expression of ER receptors." (PMID 37511437, 2023). "The CaSR has more recently been studied as a hypothetical predictive marker for skeletal metastases in breast carcinoma, and it was shown that in patients with advanced, metastatic breast cancer, CaSR expression was higher in those with skeletal metastases." (PMID 37511437, 2023). "Based on recent findings, we aimed to explore the correlation between CaSR expression and different pathohistological prognostic factors of breast cancer." (PMID 37511437, 2023). "In breast cancer cells, the CaSR acts as an oncogene and promotes tumor growth through mechanisms that are not yet fully understood." (PMID 37511437, 2023). "All of the mentioned studies highlight the important role of the CaSR in the development and progression of breast cancer." (PMID 37511437, 2023). "It was observed that reducing the expression of CaSR in vivo and in vitro inhibited the production of PTHrP and reduced the growth of the breast cancer." (PMID 33796580, 2021). "Treatment of breast cancer cells with siRNAs that target the CaSR reduced receptor expression and decreased cell proliferation." (PMID 34223822, 2021). "However, whether the difference in circulating calcium levels and /or the expression of CASR variants at whether rs1801725 underlies the disparate aggressiveness of especially prostate and breast cancers in patients of African versus European ancestries remains to be clearly delineated." (PMID 34357109, 2021). "In maternal breast tissues the CaSR promotes lactation but in breast cancer it acts as an oncoprotein and has been shown to drive the pathogenesis of skeletal metastases from breast cancer." (PMID 32117726, 2020). "Previously we tested MEMRI as imaging tool to report on the high expression levels of Calcium Sensing Receptor (CaSR) in a human breast cancer animal model." (PMID 32931488, 2020). "Bone marrow stromal cells and osteoblasts express the PTH1R which binds to PTHrP produced by skeletal metastatic breast cancer cells initiating the vicious cycle and is exacerbated by the calcium-CaSR signaling." (PMID 32117726, 2020). "This review focuses on how the CaSR leads to the pathogenesis of breast cancer by contrasting its role in healthy tissues and tumorigenesis, and by drawing brief parallels with the tissues where it has been implicated as an oncogene." (PMID 32117726, 2020).
breast carcinoma (continued). "In our previous study, we applied MEMRI to image breast cancer tumours with a high-level expression of CaSR." (PMID 32931488, 2020). "Current clinical therapies for treating bone metastases from breast cancer are limited to targeting osteoclasts and a deeper understanding of the CaSR signaling nexus in this context can bolster them or lead to novel therapeutic interventions." (PMID 32117726, 2020). "In all these types of cancer where the CaSR is upregulated or acts as an oncogene, like in breast cancer, the effect of calcilytics in impeding metastasis is highlighted." (PMID 32117726, 2020). "In fact, CasR stimulates the proliferation of breast cancer cells and mediates the promoting effect of extracellular calcium on bone metastasis." (PMID 33113952, 2020). "Activation of the CaSR in breast cancer cells have also been shown to stimulate cell proliferation acting through membrane metalloproteinases, upregulating the transient receptor potential channel 1, stimulating EGFR, and ERK1/2 phosphorylation." (PMID 32117726, 2020). "TRPC1 can be activated by CaSR in rabbit mesenteric arteries, colonic epithelial, endothelial, and breast cancer cells, making it an ideal candidate for mediating the suppression of PTH secretion downstream of CaSR in the PTG." (PMID 32213715, 2020). "In breast cancer, CaSR activation by high calcium induces cancer cell proliferation, potentially through the EGFR-ERK1/2 axis." (PMID 29348629, 2018). "In a study of human breast cancer the overexpression of calcium-sensing receptor (CaSR) in tumour was suggested to be involved in better Mn-enhancement." (PMID 29708197, 2017). "Since PTHrP secretion by metastatic cells increases osteoblasts RANKL production and subsequent osteclastogenesis, the current prevailing view is that CaSR osteolytic potential comes from its ability to increase metastatic breast cancer cells PTHrP secretion." (PMID 28915604, 2017). "In vitro, activation of the CaSR with Ca2+, spermine, aminoglycoside antibiotics or allosteric (type II) calcimimetics increased PTHrP secretion by breast cancer cells." (PMID 28915604, 2017). "To conclude, our data revealed an important role for the CaSR-epiregulin axis on metastatic breast cancer cells osteolytic potential." (PMID 28915604, 2017). "Of interest, CaSR expression is higher in breast cancer samples from patients with bone metastasis, suggesting that CaSR-positive tumors are more likely to metastasize to the skeleton." (PMID 28915604, 2017). "Overexpression of a functional CaSR in metastatic breast cancer cells dramatically amplifies their osteolytic potential through epiregulin-mediated OPG downregulation." (PMID 28915604, 2017). "In a recent experimental study on MDA-MB-231 cells, estrogen-independent breast cancer cell line prone to induce osteolytic metastasis were transfected with plasmids containing full-length wild-type CaSR." (PMID 29099748, 2017). "At site of bone resorption, the activation by Ca2+ of the CaSR expressed by metastatic breast cancer cells favors epiregulin synthesis and secretion, which in turn acts on osteoblastic cells to reduce OPG synthesis." (PMID 28915604, 2017). "To investigate the role of the CaSR on breast cancer cells osteolytic potential, we used MDA-MB-231 cells, an estrogen-independent breast cancer cell line able to colonize bone and to induce osteolytic metastasis." (PMID 28915604, 2017). "Stimulation of the CaSR has been shown to promote the migration of several metastatic bone-preferring breast cancer cell lines." (PMID 27303307, 2016). "The CaSR is expressed in both normal breast ductal epithelial cells and in primary breast cancer cells." (PMID 27303307, 2016). "The growth inhibitory effects of the CaSR in breast cancer cells have been reported to be mediated by the downregulation of the expression of survivin, a well described anti-apoptotic factor in breast and other cancers." (PMID 27746743, 2016).
breast carcinoma (continued). "In this review we will focus on the functions of the CaSR in mammary gland biology, its regulation of mammary gland PTHrP production and its contribution to the development and progression of breast cancer." (PMID 27746743, 2016). "Activation of the CaSR decreases cAMP levels in normal breast cells, but increases cAMP response in breast cancer cells." (PMID 27746743, 2016). "In the aggregate, these findings clearly suggest that the CaSR affects breast cancer cell proliferation and apoptosis, at least in part, by stimulating the production of PTHrP, which, in turn, acts in the nucleus to regulate p27kip1 and AIF levels." (PMID 27746743, 2016). "The CaSR also modulates breast cancer metastasis by mediating the secretion of parathyroid hormone-related peptide (PTHrP)." (PMID 27303307, 2016). "Subsequent reports documented CaSR expression in standard human breast cancer cell lines, such as MCF-7 and MDA-MB-231 cells." (PMID 27746743, 2016). "Together, these data demonstrate that activation of the CaSR increases PTHrP production by breast cancer cells in rodents and in humans, both in vitro and in vivo." (PMID 27746743, 2016). "CaSR stimulated secretion of PTHrP from breast cancer cells promotes osteolytic activity and is increased by transforming growth factor-β released from resorbed bone." (PMID 27303307, 2016). "Several studies have shown that the CaSR is expressed in breast carcinomas from patients and in breast cancer cell lines." (PMID 27746743, 2016). "In normal cells the CaSR couples to Gαi to inhibit cAMP and PTHrP production, whereas in breast cancer cells, it couples to Gαs to stimulate cAMP and PTHrP production." (PMID 27746743, 2016). "We found that in normal breast cells, the CaSR couples to Gαi and inhibits adenylyl cyclase while, in breast cancer cells, the CaSR couples to Gαs and stimulates cAMP production." (PMID 27746743, 2016). "Activation of the CaSR on breast cancer cells regulates breast cancer cell proliferation, death and migration, in part, by stimulating PTHrP production." (PMID 27746743, 2016). "The majority of breast cancers that metastasize to bone are estrogen receptor (ER)-positive so it is also interesting that activation of the CaSR has been shown to increase ER transcriptional activity and enhance the effects of estradiol in MCF-7 cells." (PMID 27746743, 2016). "Studies examining the effects of CaSR signaling on proliferation and cell death in breast cancer cells have reported contradictory results." (PMID 27746743, 2016). "The calcium-sensing receptor (CaSR) is expressed in normal breast epithelial cells and in breast cancer cells." (PMID 27746743, 2016). "We also found that knocking out the CaSR inhibited the proliferation of mammary tumor cells in MMTV-Cre; CaSRlox/lox; MMTV-PyMT mice in vivo, slowing the growth of tumors." (PMID 27746743, 2016). "Cells have the ability to recognize extracellular calcium by CaSR, which in some cancer entities, such as breast cancer, correlates with bone metastasis." (PMID 24576174, 2014). "Breast cancer cells highly express calcium-sensing receptor (CaSR), which could bind with Ca2+, and promote breast tumor cell spread to the bone tissue with high Ca2+ concentration." (PMID 39605887, 2024). "Yang and Wang showed that in breast cancer cells, which also metastasize to bone, CaSR activation upregulates the parathyroid hormone-related protein (PTHrP) and subsequently activates the Gs/cAMP pathway that furthers PTHrP production in a “feed-forward” loop." (PMID 38435029, 2023). "Thus using normal breast epithelial and a diverse set of breast cancer cell lines, we demonstrate that the expression of the CaSR at the mRNA level is cell type specific." (PMID 35355564, 2022). "Besides being expressed in normal breast epithelial cells, CaSR is expressed also in breast cancer cells." (PMID 35163823, 2022).
breast carcinoma (continued). "Elevated serum calcium has been coupled with poorer prognosis in breast cancer even without bone metastases, therefore polymorphisms previously predicted to decrease the sensitivity of the CaSR (A986S and Q1011E) are also in the focus in some oncological investigations concerning breast cancer." (PMID 33528764, 2021). "However, efforts aimed at deciphering the relation between CaSR and PTHrP in breast cancer demonstrated that the action of CaSR is mediated by nuclear PTHrP and partly affects proliferation and apoptosis." (PMID 32117726, 2020). "However, in a diseased setting, where there is rising evidence of the CaSR acting as an oncogene in breast cancer, it is said to facilitate a vicious cycle of osteolysis and tumor growth affecting the pathophysiology of bone metastases." (PMID 32117726, 2020). "In breast cancer cells, CaSR inhibited IL-6 secretion, while LPA and S1P enhanced IL-6 expression." (PMID 31847214, 2019). "In accordance with this hypothesis, expression of the CaSR is higher in breast cancer cell lines with relatively increased bone metastatic potential such as MDA-MB-231." (PMID 28915604, 2017). "Moreover, activated CaSR increases the activity of the PMCA2 calcium pump to protect the breast cancer cells from calcium-mediated apoptosis and governs the TRPC1 calcium channel which can stimulate proliferation." (PMID 29099748, 2017). "However, in some studies, CaSR was overexpressed in breast tumors as compared to normal mammary cells, while, in others, lower levels were found expressed in human breast cancers than in normal breast tissue." (PMID 29099748, 2017). "It is currently known that the existence of this CaSR-PTHRP axis could provide further opportunities for novel treatments of breast cancer metastases." (PMID 29099748, 2017). "This suggests that a high level of functional CaSR may be necessary for metastatic breast cancer cells to promote bone osteolysis." (PMID 28915604, 2017). "In the aggregate, these findings suggest that the CaSR may regulate cell migration in breast cancer cells, however, much more work must be done in this area to determine how important these observations in vitro are to the behavior of breast cancers in vivo." (PMID 27746743, 2016). "Interestingly, as compared to normal breast cells, in breast cancer cells, the regulation of PTHrP secretion by the CaSR becomes rewired due to a switch in its G-protein usage such that activation of the CaSR increases instead of decreases PTHrP production." (PMID 27746743, 2016). "It should also be noted that SNPs in the CASR gene locus have not been associated with breast cancer risk in GWAS studies." (PMID 27746743, 2016). "Therefore, it appears that during the transformation of normal breast cells into malignant breast cancer cells, the CaSR switches its G-protein preference, which, in turn, leads to completely opposite effects on PTHrP production." (PMID 27746743, 2016). "Understanding the diverse actions mediated by the CaSR may help us better understand lactation physiology, breast cancer progression and osteolytic bone metastases." (PMID 27746743, 2016). "Thus, altered secretion of chemotactic and pro-angiogenic cytokines in breast cancer cells is modulated by the CaSR." (PMID 27303307, 2016). "In the aggregate, these data support that notion that the CaSR promotes increased proliferation of breast cancer cells and suggest two interesting signaling pathways that may mediate these effects." (PMID 27746743, 2016). "However, a switch in CaSR G-protein usage during malignant transformation appears to convert this feedback loop into a PTHrP feed-forward cycle in breast cancer cells that exacerbates the growth of osteolytic skeletal metastases." (PMID 27303307, 2016).
breast carcinoma (continued). "It is unlikely that PTHrP mediates all of the effects of the CaSR on breast cancers but, at this point, relatively little is known about the direct effects of CaSR signaling on breast cancer cell behavior, and many of the initial observation have been contradictory." (PMID 27746743, 2016). "Data from these several studies suggest that the CaSR inhibits proliferation and promotes cell death in breast cancer cell lines, implying that it may inhibit breast cancer development and/or progression." (PMID 27746743, 2016). "Given that the CaSR upregulates PTHrP and given that PTHrP has been shown to regulate breast cancer progression, we were interested in determining whether PTHrP might mediate some of the effects of the CaSR on breast cancer cells in vitro and in vivo." (PMID 27746743, 2016). "In breast cancer, the expression of CaSR correlates with the formation of bone metastases." (PMID 24576174, 2014). "However, in other cell types, such as MCF-7 breast cancer cells and keratinocytes, CaSR activation mediates SOCE, suggesting that CaSR stimulation mediates Ca2+ entry in a cell-specific manner." (PMID 24905090, 2014). "In MCF-7 breast cancer cells, activation of the CaSR is transduced via the PI-PLC pathway into generation of IP3, which not only causes the release of Ca2+ from endoplasmic reticulum, but also evokes Ca2+ influx across the plasma membrane through non-selective cation channels (for details,)." (PMID 23340319, 2013). "Furthermore, during bone metastasis in breast cancer, CaSR promotes the adaptation of cancer cells to the bone microenvironment, while CaSR antagonists may reduce the capacity of tumor cells to invade bone by reducing Ca2+ dependent signaling." (PMID 41522513, 2026). "Moreover, we also found that high expression of CaSR was associated with a worse prognosis following chemotherapy in breast cancer patients who did not receive endocrine therapy and in ovarian cancer patients who underwent suboptimal debulking surgery." (PMID 39113697, 2024). "Our data also reveal that the expression levels, mutational status in exon 7 of the CASR as well as the Ca2+ influx dynamics do not completely explain the distinct responses of breast epithelial and breast cancer cell lines to an increase in extracellular Ca2+." (PMID 35355564, 2022). "Finally, prior results from our laboratory have demonstrated that intracrine/nuclear actions of PTHrP downstream of the calcium-sensing receptor are important in modulating cell proliferation and survival in human breast cancer cell lines and in PyMT-induced mouse mammary tumors." (PMID 35440032, 2022). "Thus, more work will be required to fully elucidate the role of the CaSR in both normal and malignant breast cells and to determine whether targeting the CaSR-PTHrP axis would be an effective strategy against breast cancers." (PMID 27746743, 2016). "Therefore, this dataset suggested a tumor suppressor role of the CaSR in breast cancer." (PMID 27303307, 2016). "Thus, extracellular Ca2+ appears to be a chemoattractant for bone preferring metastatic breast cancer cells toward a Ca2+ rich environment, and importantly, the level of CaSR expression has been shown to correlate positively with the magnitude of breast cancer metastasis potential." (PMID 27303307, 2016). "Moreover, several isoforms of TRPC channels, dependent on the cell type, have been implicated in the CaSR activation-induced Ca2+ entry, such as TRPC3 in salivary ductal cells, TRPC1 in MCF-7 breast cancer cells and keratinocytes, and TRPC6 in aortic smooth muscle cells and cardiac myocytes." (PMID 24905090, 2014). "Particularly, cross-talk between the calcium-sensing receptor and the EGFR in MCF-7 breast cancer cell proliferation has been observed, and cooperative signaling between calcium and EGF on tumor cells has also been observed." (PMID 39940827, 2025).